IL6 (interleukin 6)
Diseases named in the same sentence as IL6 in open-access papers (continued):
Sharing a sentence is not in itself a finding about the gene and the disease.
immune dysfunction (210 papers, 2004 to 2025). "Of note, IL-6 inhibitors have also been associated with an increase in BMI when used to treat immune disorders, and, in general populations, higher IL-6 levels appear to reduce appetite and regulate weight." (PMID 41323348, 2025). "It is well known that IL‐6 has a dual role, so there is a wide debate on its homeostatic and pathogenic roles in various immune diseases when considering IL‐6 as a therapeutic target." (PMID 38411379, 2024). "have also been found to positively correlate with serum interleukin-6 (IL-6) levels, and BD is strongly associated with immune dysfunction." (PMID 39564459, 2024). "Both groups also had similar underlying immune dysfunction, with upregulation of immune processes such as “Interleukin-1 signaling” and “Interleukin-6/JAK/STAT3 signaling” throughout disease compared to healthy controls." (PMID 37090709, 2023). "MCD originates due to immune dysfunction and excessive increase of cytokines caused by a variety of comprehensive factors, such as IL-6, human herpes virus-8 (HHV-8), and human immunodeficiency virus (HIV)." (PMID 38082371, 2023). "The inflammaging-associated immune dysfunction include elevated basal levels of IL-6, which transforms monocytes into antigen presenting cells to produce IL-1β and IL-23." (PMID 37266014, 2023). "Studies have shown that immune disorders in RA patients are mainly caused by the activation of specific signaling pathways by IL-6, IL-l, TNF-α, and other cytokines." (PMID 35784680, 2022). "The activation of pro-inflammatory cytokines, such as TNF-α, IL-1β, and IL-6, in intestinal inflammatory cells can cause a cascade of intestinal inflammation that leads to local inflammation and immune system disorders." (PMID 34348563, 2021). "Other biologics are actually used in MDS-associated systemic inflammatory or auto-immune disorders (such as anti-IL-1, IL-6 antibodies) but are also evaluated in combination with other drugs." (PMID 34829329, 2021). "Among the various proinflammatory cytokines, IL-6 is the main player as it elevates the activity of proinflammatory signaling pathways and is associated with a large number of immune diseases." (PMID 33330627, 2020). "Human aging is associated with systemic inflammation and oral manifestations associated with elevated IL-6 levels and immune dysfunction, although the underlying defects in immunomodulatory mechanisms are unclear." (PMID 33240286, 2020). "INF-γ, IL-12, TNF-α, and IL-6 are all pro-inflammatory cytokines which can cause immune disorders and amplify the inflammation." (PMID 28587089, 2017). "At rest, circulating concentrations of IL-6 are attributed to adipocytes and macrophages resident within adipose tissue, uraemia-induced immune dysfunction, and other causes." (PMID 23737775, 2013). "However, our nomogram model confirmed that the level of IL-6, which is the cause of host immune disorders, is an appropriate independent risk factor for predicting the occurrence of NP in children." (PMID 40399899, 2025). "As IL-6 is a pro-inflammatory cytokine and IL-10 a globally anti-inflammatory cytokine, it was somewhat expected that elevated IL-10 levels would be associated with immune dysfunction, which was confirmed in this study." (PMID 35976460, 2022). "The cited study revealed inflammation of the small intestine in pregnant sows as well as changes in newborn piglets where immune dysfunctions and increased expression of the genes encoding proinflammatory cytokines IL-6, IL-1α, IL-1β, and TNFα were observed in the small intestine." (PMID 32471145, 2020). "Therefore, we screened pro-inflammatory cytokines IL-1β, TNF-α, and IL-6, which cause immune disorders and amplify inflammation, as well as anti-inflammatory cytokine IL-10." (PMID 31500342, 2019).
immune dysfunction (continued). "Th17 cells further promote the release of pro-inflammatory cytokines such as IL-17, IL-6, and chemokines to expand the inflammatory response, which may eventually cause further immune disorders and lead to SIRS and even death." (PMID 30546828, 2018). "In addition, it has recently been demonstrated that mortality in HIV and M. tuberculosis co-infected patients is linked to immune dysfunction of monocytes, especially related to inflammatory mediator production of IL-6, TNFα, and CSF3 and expansion of CD16+CD14+ monocytes." (PMID 29770360, 2018). "Age-related immune dysfunction (including reduced T-cell activity,impaired antibody production, and elevated cytokines such as IL-6 and TNF-α) isassociated with severe outcomes, such as cytokine storms and multi-organ failure." (PMID 41337512, 2025). "By lowering LDL-C, T-cell exhaustion, and IL-6 in participants with elevated inflammation, AD can reduce metabolic and immune dysfunction in PLWH." (PMID 41294355, 2025). "Preparations from Hericium coralloides and T. versicolor rebalanced cytokine profiles in immune cells from older adults, reducing IL-5 and IL-13 while adjusting IL-1β, IL-6, and interferon levels—an effect relevant to age-related immune dysfunction." (PMID 41488566, 2025). "Studies have shown that excessive alcohol intake increases pro-inflammatory cytokines, such as TNF-α and IL-6, contributing to chronic inflammation and immune dysfunction." (PMID 39846539, 2025). "Interleukin-6 (IL-6) has been used as an inflammatory marker in the clinical evaluation of patients with inflammation, infections, or immune disorders." (PMID 40420944, 2025). "These ATMs promote systemic inflammation by increasing the production of cytokines such as tumor necrosis factor-alpha (TNF-α) and interleukin 6 (IL-6), thereby maintaining a vicious cycle of immune dysfunction." (PMID 40564149, 2025). "Fact: Endometriomas are associated with elevated levels of pro-inflammatory cytokines (e.g., IL-6, IL-8, IL-1β) and immune dysfunction, contributing to disease progression." (PMID 40217598, 2025). "Higher CRP and IL-6 levels in this group align with prior research linking immune dysfunction to muscle wasting and reduced physical resilience." (PMID 40277851, 2025). "The simultaneous overexpression of TNF-α and IL-6 in PPT-exposed rats indicates immune system disorder and severe damage in lung tissue." (PMID 40277406, 2025). "IL-6 (interleukin-6) plays an irreplicable role in the infectious and inflammatory process in the human body, related to immune disease and neuroinflammation." (PMID 41370283, 2025). "B cells in RA synovium induce the production of cytokines such as IL-1α, IL-23, IL-12, IL-6, and TNF-α, causing bone damage, inflammation, and immune disorders." (PMID 39139563, 2024). "TET2 has various mechanisms in neoplastic and immune diseases and downregulates the expression of inflammatory cytokines IL-6 and IL-1β through recruiting HDAC enzymes for histone deacetylation in innate myeloid cells and macrophages." (PMID 39659792, 2024). "These EDCs disrupt the normal functioning of hormones in males and elevate the levels of pro-inflammatory cytokines such as IL-1b, IL-2, IL-6, IL-10, and IL-17A, leading to immune system disorders." (PMID 39636940, 2024). "The significant inhibition of M. comosus extracts against IL-1β, TNF-α and IL-6 makes it a potential therapeutic target against multiple immune disorders." (PMID 38310564, 2024). "IL6 is an inflammatory cytokine produced by various cells and participates in the pathogenesis of immune disorders, exerting multiple effects." (PMID 37304306, 2023). "CRP, PCT and IL-6 all showed significant increases in non-immune diseases than IM and immune diseases, with the value of 18.8 ± 1.4 mg/L (p<0.001), 1.5 ± 0.4ng/L (, p=0.001), and 121.4 ± 22.5pg/mL (, p<0.01), respectively." (PMID 37026057, 2023).
immune dysfunction (continued). "PGE2 is the most abundantly detected PG in various tissues and has been shown to promote the production of various pro-inflammatory factors (such as IL-1β, IL-6, and IL-12) in immune diseases." (PMID 36937256, 2023). "We analyzed plasma concentration of four pro-inflammatory cytokines (TNF-alfa, IFN-gamma, IL-6 and MCP-1) that have reported as dysregulated in AT-associated immune disorders." (PMID 37668709, 2023). "On the other hand, during the active phase of CHB, immune system disorders aggravated liver cell necrosis, increasing tumor necrosis factor, endotoxin, and various cytokines (such as interleukin-1 and interleukin-6)." (PMID 35402467, 2022). "The immune dysfunctions of SSc patients are manifested by excessive production of proinflammatory cytokines IL-1, IL-6, IL-17, IFN-α, and TNF-α, which can elicit potent tissue inflammation followed by tissue fibrosis." (PMID 34943909, 2021). "Although other novel anti-IL6 antibodies are being assessed for the treatment of immune disorders or COVID19 (NCT04348500), further work is needed to evaluate their potential against BC." (PMID 34834425, 2021). "Proinflammatory cytokines TNF-α and IL-6 have been reported to result in mucosal inflammation and aggravate immune disorders." (PMID 34195297, 2021). "The upregulation of NEAT1 has been shown to promote the release of several inflammasomes (NLRP3, NLRC4, and AIM2) and pro-inflammatory cytokines (CXCL10, IL-6, and IL-1β), resulting in an immune response in inflammatory and immune diseases." (PMID 35127819, 2021). "IL-6 can differentiate naïve CD4+ αβT cells into Th17 cells which contributed to the pathophysiologic process of immune disorders." (PMID 33902534, 2021). "A novel mechanism of DC-dependent CD4+ T cell immune dysfunction was attributed to IL-6 overproduction." (PMID 32542025, 2020). "As one of the main controllers of the immune response, many pro-inflammatory cytokines such as IL-6, IL-1β, and TNF-α have been reported to respond to stress and immune disorders, and IL-6-related pathways also play a key role in regulating acute heat stress." (PMID 33233727, 2020). "Introduction of CARDS toxin caused damage to mouse lung tissues, accompanied by the increase of the expression of the pro-inflammatory cytokines (such as TNF-α and IL-6) and immune disorders." (PMID 31399022, 2019). "Patients with a higher immune dysfunction score also had higher IL-6 and TNF-α elevation ratios after LPS stimulation." (PMID 29073262, 2017). "This has stimulated epidemiological assessment of several biomarkers of inflammation and immune dysfunction, including C-reactive protein (CRP), interleukin-6 (IL-6) and D-dimer and their associations with age-related morbidity and HIV infection." (PMID 23994067, 2013). "Immune system disorders can result from immunosenescence, a condition where the immune system can become exhausted, chronic low-inflammatory triggers arise because of consistently higher levels of IL-6, and T-lymphocyte subsets are abnormally activated." (PMID 38892281, 2024). "By reducing LDL-C levels, lowering immune cell activation and T-cell exhaustion, and conferring a reduction in IL-6 in participants with elevated inflammation, the AD could serve as a powerful tool in reducing metabolic and immune dysfunction in PLWH." (PMID 39606458, 2024). "The abnormal expression of inflammatory factors such as TNF-α, IL-1β, IL-6 and IL-17 might affect the pathophysiological processes such as intestinal flora imbalance and immune dysfunction in DC patients." (PMID 36998438, 2023). "Future studies could also investigate whether there is an association between functional connectivity and performance measures of fatigue and inflammatory or immune disease markers (e.g., IL-6)." (PMID 37332875, 2023). "Patients in the UTI group may have had immune dysfunction, thus leading to a significant increase in the serum levels of IL-1β and IL-6." (PMID 35531475, 2022).
immune dysfunction (continued). "Antibiotics induced immune dysfunction resulted in disproportionate release of cytokines and increased intestinal mucosal inflammation, including higher expression levels of IL-1β, IL-6, and TNF-α, which were considered as common biomarkers in various inflammatory conditions." (PMID 36726819, 2022). "Inflammatory molecules, including IL-6, inhibit HLA-DR and induce PD-L1 expression, suggesting that the high level of plasmatic IL-6 observed in COV patients may exacerbate the immune dysfunction of these patients." (PMID 35710943, 2022). "Local synthesizing process for cytokine (e.g., IL-1α, IL-23, IL-12, IL-6, and TNF-α) under the induction from local autoreactive B cell was suggested to impact pathology-associated RA cells, triggering bone injury, inflammation, and immune disorder." (PMID 34691030, 2021). "Chronic inflammation is due to uncontrolled infiltration by inflammatory and immune cells, and the release of pro-inflammatory mediators such as tumor necrosis factor-α (TNF-α), interleukin-1β (IL-1β), and interleukin-6 (IL-6), which leads to disruption of homeostasis and immune system disorders." (PMID 34504137, 2021). "TNF-α, IL-1, IL-6, IL-8, and IL-10 can be secreted from monocytes/macrophages, whereby inflammatory cascade activation plays a major role in the development of immune dysfunction and multiple organ dysfunction following polytrauma." (PMID 34876907, 2021). "Moreover, the nanodecoys efficiently bound and neutralized inflammatory cytokines, such as IL-6 and GM-CSF, and effectively suppressed the immune disorder and lung injury in an ALI mouse model." (PMID 33024017, 2020). "Interestingly, inflammatory mediators such as CRP, TNF-α, IL-1ra, IL-6, IL-8, and IL-10 have been identified to be part of both: age-related diseases and trauma-induced immune dysfunction." (PMID 32258173, 2020). "The reduced levels of IL-4 and IL-6 and phosphorylation of p38, IκB-α, and p65 in the jejunum further confirmed that FMS reduced the immune disorder that might be caused by antigenic proteins." (PMID 32047057, 2020). "An elevated level of IL-6 signaling may negatively affect homeostasis and IL-6 involved in the pathogenesis of immune diseases and chronic inflammatory conditions like RA and play a main role in articular manifestation of the disease." (PMID 31057960, 2019). "Once LPS is released into the blood system, it can trigger monocytes and phagocytic cells to secrete large amounts of various pro-inflammatory cytokines such as TNF-α, IL-6, IL-1β and various others that contribute to the pathophysiology of septic shock and other immune diseases." (PMID 30065898, 2018). "Previous studies suggested that CD is a T helper 1-mediated immune disease characterized by increased cytokine levels of IFN-γ, TNF-α, and IL-12, whereas UC is a T helper 2-mediated immune disease characterized by increased cytokine levels of IL-6 and/or reduced IL-10." (PMID 28683149, 2017). "Otherwise, a complete thymic atrophy by abnormal high MT-I+II and III, via high IL-6 may provoke continuous immune dysfunctions (thymic and extrathymic)." (PMID 15679929, 2004). "Additionally, multiplex cytokine analysis revealed significant elevations in Eotaxin, IL-1β, IL-4, IL-6, IL-8, MIP-1α, and TNF-α in SZ patients, whereas IFN-γ, IL-9, IL-1ra, IL-13, MCP-1, MIP-1β, and RANTES were reduced (p < 0.05), indicating a complex immune dysfunction associated with SZ." (PMID 40761785, 2025). "In addition, increased IL-6 levels were significantly associated with low CD4+ T lymphocyte counts, which in fact has already been observed in baseline studies and is associated with immune dysfunction." (PMID 38992229, 2024). "IL-6, on the other hand, plays a crucial role in the formation of Th17 cells, and it stimulates the release of diverse inflammatory substances that may lead to immune disorders and chronic inflammation." (PMID 29391009, 2018).
immune dysfunction (continued). "Therefore, IL-6 triggered an immune disorder by breaking the balance between Th17 and Treg." (PMID 27852285, 2016). "Abnormally high baseline values of IFN-γ, IL-6, and TNF-α were observed in one patient at DL 400 mg who experienced treatment-emergent grade 3 nausea and grade 4 immune system disorder (hypersensitivity)." (PMID 40875525, 2025). "Cytokine profiling showed decreased levels of IL-2, IL-6, IL-10, TNF-α, and IFN-γ, indicating broad-spectrum immune dysfunction." (PMID 40806124, 2025). "IL-6 promotes HS-CRP secretion, resulting in immune dysfunction and aggravation of inflammatory responses." (PMID 40837367, 2025). "Purpurin played an anti-inflammatory role by inhibiting IL-6, TNF-α, and IL-1β and increasing IL-10, and regulated immune disorder by decreasing the CD4+/CD8+ ratio and increasing the FOXP3 level." (PMID 36615560, 2023). "Increased levels of proinflammatory mediators from M1-type macrophages lead to inflammation and immune disorders, such as TNF-α, IL-6, and IL-1β." (PMID 37035757, 2023). "Data from previous studies had shown the frequency of IL-6-producing TrB cells to be elevated in SLE, SS, and other immune diseases." (PMID 32183811, 2020). "IL-6 is also produced by TrB cell and the frequency of IL-6-producing TrB cells was seen to be elevated in patients with SLE, SS and other immune diseases." (PMID 32183811, 2020). "The imbalance of proinflammatory cytokines, such as IL-6, TNF-α, IL-1β, and IL-10, was demonstrated that contributed to immune dysfunction and also mediated inflammation of the tissues and organ damage in SLE." (PMID 31886314, 2019). "In our series, patients with higher monocyte IL-6 and TNF-α production after re-exposure to LPS had higher 28-day mortality rates and immune dysfunction score." (PMID 29073262, 2017). "Both endogenous and exogenous IL-37 have been shown to ameliorate inflammation and regulate immune disorder via inhibiting the production of inflammatory mediators including IFN-γ, TNF-α, IL-6, and IL-18." (PMID 28781417, 2017). "Recently, a number of biologic agents targeting inflammatory cytokines, such as IL-6, IL-1β and TNF-α have been developed and used as therapeutics for RA and other immune disorders." (PMID 27070121, 2016). "Biomarkers such as C-reactive protein (CRP), interleukin-6 (IL-6), and tumor necrosis factor-alpha (TNF-α) have been shown to correlate with systemic inflammation and immune dysfunction, which may play a role in the development of GI side effects." (PMID 39860995, 2025). "Because of the immune dysfunction, CRF patients secrete too much IL-17 and IL-6." (PMID 33101444, 2020). "Moreover, the stimulated macrophages produce large amounts of inflammatory cytokines, including TNF-α, IL-1β and IL-6, and TNF-α, which evoke the production of other inflammatory cytokines and leads to multiple immune disorders and pain." (PMID 29391009, 2018). "Furthermore, we found that levels of salivary IL-6, IFN-γ, IL-10, IL-17A, and TNF-α in OLP patients were significantly upregulated, likely because of the oral immune disorder." (PMID 28400582, 2017). "CSF CXCL13, CXCL10, IL-6 and IFN-α are elevated in a number of infectious and immune disorders." (PMID 27575749, 2016). "Therefore, IL-6 is evidently a key molecule in SIV infection, since circulating IL-6 levels consistently correlate with residual HIV viremia and markers of immune dysfunction in HIV infection." (PMID 27484833, 2016). "Consistently, we demonstrated that the BM plasma IL-6 level was also markedly elevated in ND AML patients, which indicated that there is an immune disorder, which may affect AML progress through effect factors." (PMID 26134277, 2015). "Second, we could not conclude that a higher NLR or IL-6 level represents a fatal immune disorder or inflammatory storm from our study." (PMID 33796105, 2021).